Y_RNA (Y RNA )
Gene: Miscellaneous RNA gene on chromosome 2 (25,008,845 to 25,008,946, reverse strand). Ensembl gene ENSG00000207069.
Homologues: Orthologues: macaque Y_RNA (98% identical), chimpanzee Y_RNA (97% identical). Paralogues in human: Y_RNA (91% identical), RNY3 (90% identical), Y_RNA (90% identical), Y_RNA (89% identical), Y_RNA (88% identical), RNY3P1 (87% identical), Y_RNA (87% identical), Y_RNA (86% identical), RNY3P14 (85% identical), RNY3P16 (85% identical), Y_RNA (85% identical), RNY3P9 (84% identical), and 96 more.